SLC31A2 (solute carrier family 31 member 2)
Description:
Does not function as a copper(1+) importer in vivo (By similarity). However, in vitro functions as a low-affinity copper(1+) importer. Regulator of SLC31A1 which facilitates the cleavage of the SLC31A1 ecto-domain or which stabilizes the truncated form of SLC31A1 (Truncated CTR1 form), thereby drives the SLC31A1 truncated form-dependent endosomal copper export and modulates the copper and cisplatin accumulation via SLC31A1 (By similarity).
Synonyms: hCTR2; COPT2; CTR2
Tractability: Antibody: its Gene Ontology location is reachable by antibodies, with high confidence; UniProt predicts a signal peptide or a membrane-spanning region; the Human Protein Atlas places it where antibodies can reach. PROTAC: UniProt records ubiquitination sites on it.
Gene: Protein-coding gene on chromosome 9 (113,150,976 to 113,164,140, forward strand). Ensembl gene ENSG00000136867.
Subcellular location: Membrane; Cytoplasmic vesicle membrane; Late endosome membrane; Lysosome membrane
Subcellular location (Human Protein Atlas): Plasma membrane; Intermediate filaments; Nuclear speckles
Gene Ontology:
Molecular function: copper ion transmembrane transporter activity; protein binding
Biological process: copper ion import; copper ion transport; regulation of copper ion transmembrane transport; copper ion transmembrane transport
Cellular component: cytoplasmic vesicle membrane; late endosome membrane; lysosomal membrane; membrane; plasma membrane; late endosome; recycling endosome
Genetic constraint (gnomAD): Loss-of-function variants: 16 observed, 14.52 expected, observed/expected ratio (o/e) 1.1, 90% interval 0.74 to 1.65. The upper end of that interval is the gene's LOEUF score, 1.65, which puts it in group 6 of 6, group 1 being the genes least tolerant of losing a copy. Missense variants: 140 observed, 180.78 expected, observed/expected ratio (o/e) 0.77, 90% interval 0.67 to 0.89. Synonymous variants: 56 observed, 72.31 expected, observed/expected ratio (o/e) 0.77, 90% interval 0.62 to 0.97.
Homologues: Orthologues: chimpanzee SLC31A2 (99% identical), macaque SLC31A2 (85% identical), rabbit SLC31A2 (78% identical), rat Slc31a2 (76% identical), mouse Slc31a2 (75% identical), pig SLC31A2 (73% identical), guinea pig SLC31A2 (73% identical), dog SLC31A2 (63% identical), tropical clawed frog slc31a2 (45% identical), zebrafish slc31a2 (41% identical), Drosophila melanogaster Ctr1A (31% identical), Caenorhabditis elegans F27C1.2 (31% identical), and 6 more. Paralogues in human: SLC31A1 (28% identical).
Diseases named in the same sentence as SLC31A2 in open-access papers:
SLC31A2 is named in the same sentence as 20 diseases in open-access papers, as found by Europe PMC text mining. Sharing a sentence is not in itself a finding about the gene and the disease. The quoted sentences say what the papers report.
ovarian carcinoma (7 papers, 2010 to 2023). A malignant neoplasm originating from the surface ovarian epithelium. "Recently the function of SLC31A2 has been reported to associate with the development of lung adenocarcinoma, ovarian carcinoma, hepatocellular carcinoma, and sensitivity to Cisplatin." (PMID 36973786, 2023).
atherosclerosis (1 paper, 2023). A disease characterized by the build-up of fatty material and calcium deposition in the arterial wall resulting in partial or complete occlusion of the arterial lumen. "The mechanistic roles of SLC31A1 and SLC31A2 in atherosclerosis and cardiovascular diseases need further experiments to confirm." (PMID 37324184, 2023). "Three cuproptosis-related genes—SLC31A1, SLC31A2 and SOD1 were screened out as diagnostic biomarkers for atherosclerosis." (PMID 37324184, 2023). "The AUC of these three cuproptosis-related biomarkers for atherosclerosis was 0.736, 0.838 and 0.848 respectively in the GSE100927 dataset, with SLC31A2 and SOD1 performing good diagnostic value." (PMID 37324184, 2023). "In the training dataset GSE97210, SLC31A1, ATP7A, SLC31A2, UBE2D1, CP and FDX1 were highly expressed while LOXL2, COA6 and SOD1 were lowly expressed in the atherosclerosis group as showed in the bar charts." (PMID 37324184, 2023). "The area under curve (AUC) of SLC31A1, SLC31A2 and SOD1 for the diagnosis of atherosclerosis was 0.800, 0.779 and 0.798 respectively in the GSE28829 dataset, with SLC31A1 demonstrating good diagnostic performance." (PMID 37324184, 2023). "Consistently, the atherosclerosis plaques showed significantly higher expression of SLC31A1, SLC31A2 and lower expression of SOD1 than the normal intimae." (PMID 37324184, 2023). "Consequently, SLC31A1, SLC31A2 and SOD1 were regarded as three hub cuproptosis-related biomarkers in atherosclerosis." (PMID 37324184, 2023). "In summary, we identified three hub cuproptosis-related genes—SLC31A1, SLC31A2 and SOD1 and construct a possible ceRNA network and a transcription factor regulation network in the molecular mechanism of atherosclerosis, providing new insights into cuproptosis and atherosclerosis." (PMID 37324184, 2023).
colorectal cancer (1 paper, 2024). A primary or metastatic malignant neoplasm that affects the colon or rectum. "Following CDKN2A knockout, we detected an upregulation of the copper uptake gene SLC31A2 and a downregulation of the copper efflux gene ATP7B in colorectal cancer cell lines." (PMID 38888512, 2024).
liver cancer (1 paper, 2023). An epithelial or non-epithelial malignant neoplasm that arises from the liver. "Expression of the Cu transporter genes ATP7A, ATP7B, SLC31A1 and SLC31A2 were found significantly altered in liver cancer samples with elevated Cu levels." (PMID 37324184, 2023).
myeloma (1 paper, 2013). "Interestingly, the list includes the gene SLC31A2 a membrane pump involved in resistance to alkylating drugs; FBXW7, USP6, UBE2J1 and Wnt-5a involved in ubiquitin proteasome pathways known to affect myeloma biology." (PMID 24376673, 2013).
Parkinson disease (1 paper, 2020). A progressive degenerative disorder of the central nervous system characterized by loss of dopamine producing neurons in the substantia nigra and the presence of Lewy bodies in the substantia nigra and locus coeruleus. "The genes that directly interact with PLLP are involved in cell-to-cell communication and neurological-related diseases, such as the completion and maintenance of myelin sheath (MOG), the ion transporter (SLC31A2) (Schweigel-Röntgen, 2014), and Parkinson’s disease (DBNDD2)." (PMID 33304381, 2020).
cancer (10 papers, 2010 to 2024). A tumor composed of atypical neoplastic, often pleomorphic cells that invade other tissues. "The qRT-PCR results from 10 paired LUAD samples showed that the expression of SOD3 and SLC31A2 in cancer tissues was significantly lower than that in normal lung tissues, whereas LOXL2 has highly expression in LUAD tissues (P < 0.05)." (PMID 36524120, 2022).
tumor (10 papers, 2014 to 2024). "The SLC31A2 and COL4A5 genes were identified to be associated with tumor resistance to most chemotherapies." (PMID 36513682, 2022). "In particular, SLC31A2 and PIK3CA were copper homeostasis-regulated genes with a key role in tumor." (PMID 36973786, 2023). "SL exposure also induced changes in the expression of genes involved in metabolic functions in tumor and stem cells (ALDH1B1, ABCB1, SLC3A2, SLC44A2, SLC31A2, SLC7A11, CYP24A1, PTGS2/COX2, PPRC1), cytokines (CCL3L3, GDF15) and growth and differentiation factors (PGF, TGFBR11 and FOXD1)." (PMID 24742967, 2014).
SLC31A2 also shares sentences with these, for which no sentence is quoted: cardiovascular disease (2 papers); heart disease (2); lung adenocarcinoma (2); ovarian tumor (2); cataract (1); clear cell renal cell carcinoma (1); COVID-19 (1); Diabetes (1); hepatocellular carcinoma (1); infection (1); iron deficiency (1); virus infection (1).